DAB2IP (DAB2 interacting protein)
Diseases named in the same sentence as DAB2IP in open-access papers (continued):
Sharing a sentence is not in itself a finding about the gene and the disease.
gastric cancer (5 papers, 2018 to 2025). A primary or metastatic malignant neoplasm involving the stomach. "Since DAB2IP expression is downregulated in gastric cancer tissues, we thus asked whether DAB2IP has a causal role in regulating gastric cancer cell phenotypes." (PMID 29743885, 2018). "In gastric cancer, DAB2IP upregulation impaired cell proliferation and sensitized cancer cells to cisplatin, while DAB2IP depletion had opposite effects." (PMID 38902547, 2024). "Our results revealed that silencing DAB2IP reduced E-cadherin expression but increased vimentin expression at both protein and mRNA levels, indicating that DAB2IP exerts a crucial role in modulating EMT in gastric cancer cells." (PMID 29743885, 2018). "Potential roles of DAB2IP in regulating gastric cancer cell growth and metastasis were examined by genetic manipulation in vitro." (PMID 29743885, 2018). "Strikingly, our results showed that abundant DAB2IP expression was observed in the matched paraneoplastic tissues of gastric cancer." (PMID 29743885, 2018). "We aimed to investigate the potential role of DAB2IP in the development and progression of gastric cancer." (PMID 29743885, 2018). "Herein, we detected the expression of DAB2IP in gastric tumor tissue specimens by Western blots and immunohistochemical (IHC) staining and investigated the effect of DAB2IP knockdown on gastric cancer cell proliferation and migration in vitro." (PMID 29743885, 2018). "Knockdown of DAB2IP enhanced gastric cancer cell growth and metastasis in vitro and promoted EMT progress at both protein and mRNA levels." (PMID 29743885, 2018). "In conclusion, our present study not only indicates that DAB2IP is downregulated in gastric cancer tissues compared to the adjacent normal tissues but also emphasizes the effect of DAB2IP knockdown on gastric cancer cell growth and metastasis in vitro." (PMID 29743885, 2018). "We also provided the first evidence that knockdown of DAB2IP enhanced proliferation and migration of gastric cancer cells." (PMID 29743885, 2018). "In the present study, we demonstrated for the first time that the expression of DAB2IP in gastric cancer tissue was downregulated compared to the adjacent normal tissues." (PMID 29743885, 2018). "To investigate the potential role of DAB2IP in the development of gastric cancer, we first used Western blotting to examine DAB2IP expression in human gastric cancer tissues and paired adjacent normal tissues." (PMID 29743885, 2018). "To evaluate the baseline expression levels of DAB2IP in a series of human gastric cancer cell lines, we detected the mRNA and protein expression of DAB2IP by QRT-PCR and Western blotting analysis, respectively." (PMID 29743885, 2018). "DAB2IP levels were analyzed in human gastric cancer and adjacent normal tissues by Western blots and immunohistochemistry." (PMID 29743885, 2018). "Finally, the E3 ubiquitin-ligase SMURF1 (SMAD ubiquitylation regulatory factor-1), was reported to induce DAB2IP ubiquitination and elimination, promoting proliferation and invasion of ovarian and gastric cancer cells." (PMID 38902547, 2024). "This may highlight a new entry point for treating gastric cancer by targeting the DAB2IP/ERK1/2 signaling axis." (PMID 29743885, 2018). "Moreover, we reveal a critical mechanism for DAB2IP in the regulation of gastric cancer tumorigenesis and metastasis through its participation in EKR1/2 signaling pathway." (PMID 29743885, 2018). "On the contrary, the expression of DAB2IP was obviously lower in the primary gastric cancer tumors." (PMID 29743885, 2018). "We next investigated the relationship between DAB2IP expression levels and the clinicopathologic status of patients with gastric cancer and found that reduced DAB2IP in gastric cancer cells was significantly correlated with tumor size, lymph node metastasis, and TNM stage." (PMID 29743885, 2018).
gastric cancer (continued). "However, there are just two studies focusing on DAB2IP in gastric cancer, which indicate that DAB2IP methylation is frequently present in gastrointestinal tumors and the resulting gene silencing plays an important role in gastrointestinal carcinogenesis." (PMID 29743885, 2018). "Since DAB2IP is involved in gastric cancer metastasis, it is possible that DAB2IP may regulate EMT progress, which is an early event in the metastasis of cancer." (PMID 29743885, 2018). "DAB2IP level is lower in gastric cancer tissues as compared to paired normal tissues." (PMID 29743885, 2018). "Inhibition of DAB2IP enhances gastric cancer cell growth and metastasis through targeting the ERK1/2 signaling, indicating that it may serve as a potential target for treatment of gastric cancer." (PMID 29743885, 2018). "Thus, more research should be undertaken to further explore the function of DAB2IP in gastric cancer." (PMID 29743885, 2018). "In accordance with other studies, blockade of DAB2IP enhanced the phosphorylation of ERK1/2 in gastric cancer cells and the enhanced proliferation and migration ability induced by DAB2IP knockdown was remarkably reduced after incubation with U0126 in SGC7901 gastric cancer cells." (PMID 29743885, 2018). "However, studies focusing upon DAB2IP in gastric cancer are scanty." (PMID 29743885, 2018). "However, the functional role of DAB2IP and the concrete molecular mechanisms in gastric cancer remain unclear and need to be explored." (PMID 29743885, 2018). "As expected, we found that knockdown of DAB2IP obviously augmented the level of phosphorylated ERK1/2 (p-ERK1/2) in both AGS and SGC7901 gastric cancer cells." (PMID 29743885, 2018). "Our in vitro studies demonstrate that DAB2IP functions as a novel regulator for ERK1/2 signaling pathway to mediate gastric cancer cell growth and metastasis and reveal its potential implications for new approaches to gastric cancer therapy." (PMID 29743885, 2018). "Firstly, we did not investigate the effect of depletion of DAB2IP on gastric cancer tumorigenesis and metastasis in vivo." (PMID 29743885, 2018). "In view of the important role of EMT in tumor metastasis during tumor progression, we explored the effect of DAB2IP on EMT progress and revealed that DAB2IP can modulate the expression of EMT marker E-cadherin and vimentin in AGS and SGC7901 gastric cancer cells." (PMID 29743885, 2018). "Secondly, DAB2IP overexpression in gastric cancer cells was not carried out because we failed to construct the expressing vector due to the long coding domain of DAB2IP gene." (PMID 29743885, 2018). "Furthermore, EMT induced by DAB2IP knockdown was reversed after treatment with U0126 in both AGS and SGC7901 gastric cancer cells." (PMID 29743885, 2018).
metastatic prostate carcinoma (5 papers, 2011 to 2015). A carcinoma that arises from the prostate gland and has spread to other anatomic sites. "Interestingly, in metastatic prostate cancer cells DAB2IP appears to directly associate with GSK3β and form a complex with phosphatase 2A and axin, a component of the β-catenin destruction complex." (PMID 24073285, 2013). "In metastatic prostate cancer (PCa), DAB2IP expression is often down-regulated and results in PI3K/Akt activation and ASK1-JNK inactivation leading to accelerated PCa growth." (PMID 26587829, 2015). "Restoring DAB2IP may also improve castration resistance in addition to radiation resistance as DAB2IP expression inversely correlates with androgen receptor activation status particularly in recurrent or metastatic prostate cancer patients." (PMID 26471467, 2015).
atherosclerosis (4 papers, 2017 to 2026). A disease characterized by the build-up of fatty material and calcium deposition in the arterial wall resulting in partial or complete occlusion of the arterial lumen. "DAB2IP-encoded ASK1/AIP1 also suppresses atherosclerosis by limiting hyperlipidemia-induced inflammation and vascular endothelial dysfunction." (PMID 34140969, 2021). "Both global gene knockouts and deletion of DAB2IP specifically in vascular endothelial cells consistently resulted in enhanced inflammatory responses, atherosclerosis exacerbation, and graft arteriosclerosis progression." (PMID 34140969, 2021). "On our previous studies, we found that high fat diet could induce development of mouse atherosclerosis by promoting the expression of the DAB2IP/ASK1 pathway in vascular endothelial cells." (PMID 33166004, 2021). "DAB2IP has multiple lines of evidence for protection against atherosclerosis." (PMID 34140969, 2021). "However, the molecular mechanisms of DAB2IP in regulating the progression of atherosclerosis need further investigation." (PMID 28962556, 2017). "Therefore, we have reason to believe that DAB2IP/ASK1 signal pathway is closely related to vascular injury and atherosclerosis induced by high‐fat diet." (PMID 33166004, 2021).
clear cell renal cell carcinoma (4 papers, 2019 to 2025). "It has also been reported that DAB2IP is functionally involved in angiogenesis in clear cell renal cell carcinoma." (PMID 40263693, 2025). "For instance, in clear cell renal cell carcinoma (CCRC), depletion of DAB2IP was correlated to AKT-dependent inactivation of p27, with increased proliferation and tumor growth in mouse xenografts." (PMID 38902547, 2024). "Consistently, UXT is upregulated in renal clear cell carcinomas and highly negative correlates with DAB2IP expression." (PMID 31481081, 2019).
glioblastoma (4 papers, 2019 to 2025). The most malignant astrocytic tumor (WHO grade IV). "In glioblastoma multiforme (GBM), DAB2IP negatively regulated ATG9B expression and inhibited tumour autophagy by blocking the Wnt/β‐catenin pathway." (PMID 36536485, 2022).
coronary heart disease (3 papers, 2013 to 2017). "Our study aims to explore the association of rs7025486 single-nucleotide polymorphisms (SNP) in DAB2IP and rs1333049 on chromosome 9p21.3 with the coronary artery disease in Chinese population." (PMID 28962556, 2017). "A genome-wide association study found the rs7025486 variant in DAB2IP associated with coronary heart disease, which was replicated in a second study." (PMID 29221435, 2017). "A variant in DAB2IP has been associated with coronary heart disease in two studies, indicating that this gene might also play a crucial rule for the normal functioning of the heart." (PMID 29221435, 2017).
esophageal squamous cell carcinoma (3 papers, 2022 to 2024). Esophageal squamous cell carcinoma (ESCC) is a type of esophageal carcinoma (EC) that can affect any part of the esophagus, but is usually located in the upper or middle third. "DAB2IP belonged to the Ras GTPase-activating protein family and played an anti-tumor role in multiple cancers, such as esophageal squamous cell carcinoma, and triple-negative breast cancer." (PMID 38440732, 2024). "In esophageal squamous cell carcinoma (ESCC) cells, expression of DAB2IP was shown to reduce resistance to ionizing radiation; in vitro, DAB2IP overexpressing cells displayed higher apoptosis after cisplatin treatment and IR exposure." (PMID 38902547, 2024). "However, the molecular status and function of the DAB2IP gene in esophageal squamous cell carcinoma (ESCC) patients who received definitive chemoradiotherapy is rarely reported." (PMID 35248066, 2022).
osteosarcoma (3 papers, 2019 to 2022). A usually aggressive malignant bone-forming mesenchymal neoplasm, predominantly affecting adolescents and young adults. "Moreover, it has been reported that has-circRNA-5692 can be used as a sponge of miR-328-5p, regulating the expression of the downstream gene DAB2IP and inhibiting the progression of liver cancer, but there are few reports about circRNA in osteosarcoma." (PMID 35682879, 2022).
premature ovarian failure (3 papers, 2021 to 2022). "Recent studies have shown that miRNA-146 can reduce premature ovarian failure in mice, and miRNA-146 overexpression can inhibit DAB2IP/ASK1/p38 MAPK pathway and γH2A." (PMID 35531876, 2022). "We also reported epigenetic mechanisms of action subserving the dietary effects of HFHS, leading to ovarian granulosa cell ageing and premature ovarian failure by inhibiting endogenous miR‐146, activating the DAB2IP/ASK1/p38‐signalling pathway and inducing γ‐H2A.X phosphorylation modification." (PMID 34180104, 2021). "However, whether there is a close relationship between DAB2IP/ASK1 pathway and premature ovarian failure induced by high‐fat and high sugar diet has not been studied in depth." (PMID 33166004, 2021).
triple-negative breast carcinoma (3 papers, 2023 to 2024). An invasive breast carcinoma which is negative for expression of estrogen receptor (ER), progesterone receptor (PR), and human epidermal growth factor receptor 2 (HER2). "Similarly, DAB2IP loss contributes to docetaxel (DOC) resistance in triple-negative breast cancer (TNBC)." (PMID 38902547, 2024). "Importantly, similar results were obtained in the triple-negative breast cancer cell line MDA-MB-231, where disruption of the actin cytoskeleton reduced DAB2IP in low density, but had negligible effects in high-density conditions." (PMID 37444489, 2023).
Alzheimer disease (2 papers, 2025 to 2026). A progressive, neurodegenerative disease characterized by loss of function and death of nerve cells in several areas of the brain leading to loss of cognitive function such as memory and language. "DAB2IP exhibited hypomethylation and increased expression, known to be associated with upregulated endoplasmic reticulum stress, which has been implicated in Alzheimer's disease, Parkinson's disease, and amyotrophic lateral sclerosis." (PMID 39953812, 2025).
Aortic dissection (2 papers, 2022). Aortic dissection refers to a tear in the intimal layer of the aorta causing a separation between the intima and the medial layers of the aorta. "New genes (MLX, DAB2IP, EP300, ZFYVE9, PML, PRKCD) were suggested as candidate aortic dissection-associated genes, through correlation analyses performed on the results of a WES study on a cohort of 99 Chinese cases." (PMID 35892496, 2022).
arterial hypertension (2 papers, 2023). "A list of differentially methylated genes could be replicated, especially the well-known hypertension-associated gene DAB2IP." (PMID 36869404, 2023).
cervical cancer (2 papers, 2025). A primary or metastatic malignant neoplasm involving the cervix. "To confirm that DAB2IP regulates DNA synthesis, we knocked down DAB2IP in the cervical cancer line HeLa cells and then assessed EdU incorporation." (PMID 41261855, 2025).
endometrial cancer (2 papers, 2017 to 2021). Primary or metastatic malignant neoplasm involving the endometrium (mucous membrane that lines the endometrial cavity). "The finding that DAB2IP was mutated in only one endometrial cancer sample indicates tissue specificity for this particular gene mutation." (PMID 27907910, 2017). "Although the mutation frequency in the DAB2IP MNR was similar (11/23), only one endometrium cancer sample displayed a mutation in the repeat." (PMID 27907910, 2017). "We identified PRRT2 and DAB2IP to be frequently mutated in MMR deficient cell lines, colorectal and endometrial cancer patient samples." (PMID 27907910, 2017). "To further evaluate the significance of the mutation frequency of PRRT2 and DAB2IP in clinical MSI colorectal and endometrial cancer patient samples, we compared their frequency to the average mutation frequency for common MSI target genes published in databases (SelTarbase)." (PMID 27907910, 2017).
melanoma (2 papers, 2016 to 2025). A malignant, usually aggressive tumor composed of atypical, neoplastic melanocytes. "Altogether, DAB2IP is robustly expressed in control tissue and retained in epithelioid melanoma, but significantly downregulated in RB, mixoid melanoma, and spindle melanoma, suggesting that loss of this tumor suppressor may accompany neoplastic progression in specific ocular malignancies." (PMID 41374987, 2025). "GIPC1 and DAB2IP expression were preserved in epithelioid melanoma yet significantly reduced in retinoblastoma and mixoid/spindle melanomas." (PMID 41374987, 2025). "GIPC1 and DAB2IP were preserved in epithelioid melanoma and reduced in RB and mixoid or spindle melanomas." (PMID 41374987, 2025). "Tumor suppressive function of NF1 (neurofibromatosis type 1) in several cancer types including melanoma, DAB2IP in prostate cancer, RASAL2 in breast cancer, PLXNC1 (Plexin C1) and RASA2 in melanoma have been described." (PMID 26993606, 2016).
non-small cell lung carcinoma (2 papers, 2020 to 2022). A group of at least three distinct histological types of lung cancer, including non-small cell squamous cell carcinoma, adenocarcinoma, and large cell carcinoma. "Here, using two non-small cell lung carcinoma (NSCLC) cell lines, one harboring a fast-cycling KRAS mutation and one with wildtype RAS, we show that RASSF1A suppression downregulates DAB2IP." (PMID 33348649, 2020).
angioedema (1 paper, 2025). Swelling involving the deep dermis, subcutaneous, or submucosal tissues, representing localized edema. "Recently and after the Symposium, families with recurrent angioedema combined with recurrent urticaria associated with mutations in either CPN1 or DAB2IP genes have been reported." (PMID 40053270, 2025). "A variant of DAB2IP was described that was associated with recurrent angioedema and occasional hives in a single Argentinian family." (PMID 40053270, 2025).
aortic aneurysm (1 paper, 2021). A ruptured aneurysm located in the wall of the proximal portion of the descending aorta proceeding from the arch of the aorta. "In prior studies, researchers had reported DAB2IP association with lower-limb ischemia and CAD case status, and with aortic aneurysm, all of which increase mortality risk in patients with CAD." (PMID 34140969, 2021).
Ataxia (1 paper, 2013). Ataxia refers to impaired coordination of voluntary muscle movement. "Dab2IP knock-down (KD) mice were viable, fertile and did not exhibit the classical reeler-like ataxia." (PMID 23326475, 2013). "Unlike reeler mice, Dab2IP knock-down mice did not exhibit severe ataxia or cerebellar hypoplasia." (PMID 23326475, 2013).
breast tumors (1 paper, 2024). "Luminal A breast tumors with low DAB2IP expression are associated with poor survival and an increased risk of recurrence." (PMID 39418101, 2024). "We found that 253 of the proposed NF-κB target genes were differentially expressed based on DAB2IP levels in Luminal A breast tumors." (PMID 39418101, 2024). "With proliferative and metastatic signatures enriched in the DAB2IP-low Luminal A breast tumors, we compared the effect of DAB2IP status on proliferation scores by molecular subtype." (PMID 39418101, 2024). "Identification of candidate NF-κB target genes in DAB2IP-low Luminal A breast tumors." (PMID 39418101, 2024). "Both NAT and grade 1 breast tumor tissues stained positively for DAB2IP." (PMID 39418101, 2024). "To examine the effect of low DAB2IP expression on the global transcriptome of all ER+ breast tumors, we performed differential expression analysis, comparing the highest and lowest quartiles of DAB2IP expression among nonbasal ER+ tumors across all subtypes (n = 320)." (PMID 39418101, 2024). "We also found that upregulated genes with low DAB2IP in Luminal A breast tumors were enriched in nonclassical estrogen and ESR1-regulated genes, which may affect responses to endocrine therapies and also drive proliferation." (PMID 39418101, 2024).
choroidal melanoma (1 paper, 2025). Malignant tumor of melanocytes of the choroid. "We examined five proteins that help cells handle nutrients and signals, Megalin, Cubilin, Caveolin-1, GIPC1, and DAB2IP, in normal eye tissue, retinoblastoma, and different forms of choroidal melanoma." (PMID 41374987, 2025).